ADAM10 (ADAM metallopeptidase domain 10)
Diseases named in the same sentence as ADAM10 in open-access papers (continued):
Sharing a sentence is not in itself a finding about the gene and the disease.
pneumonia (7 papers, 2015 to 2025). An acute, acute and chronic, or chronic inflammation focally or diffusely affecting the lung parenchyma, caused by an infection in one or both of the lungs (by bacteria, viruses, fungi, or mycoplasma.). "ADAM10 knockout in mouse alveolar epithelial cells confers resistance to lethal pneumonia caused by S. aureus." (PMID 40310291, 2025). "The loss of ADAM10 in the immune cell compartment or global loss of NLRP3 was beneficial to the host in a mouse pneumonia model of S. aureus infection, reducing mortality compared to mice with intact ADAM10 or NLRP3." (PMID 27043625, 2016). "This P. aeruginosa-triggered exosomal release of ADAM10 could constitute an essential mechanism of the pathogen to cause systemic inflammation in patients suffering from P. aeruginosa-induced pneumonia stimulating future preclinical and translational studies." (PMID 35163191, 2022). "This P. aeruginosa-triggered exosomal release of ADAM10 could constitute an essential mechanism of the pathogen to cause systemic inflammation in patients suffering from P. aeruginosa-induced pneumonia." (PMID 35163191, 2022). "Hla, for example, targets ADAM10 and Adam10-/- mice are protected from SA pneumonia with significantly decreased pathology and systemic dissemination." (PMID 25880560, 2015). "Mice lacking ADAM10 expression in the lung epithelium resist to lethal pneumonia, whereas animals lacking ADAM10 specifically on myeloid lineage develop exacerbated skin infections." (PMID 26870008, 2016).
lung fibrosis (6 papers, 2019 to 2023). "Dysregulated ADAM10 activity is implicated in a wide range of biologic processes, including immunity, lung fibrosis, Cell Adhesion and Neurite outgrowth." (PMID 36922678, 2023). "Cleavage of EPHB2 by ADAM10 in fibroblasts induces their activation and increases skin and lung fibrosis." (PMID 36835058, 2023). "In a separate model of lung fibrosis, cleavage of the ligand ephrin-B2 on fibroblasts by the disintegrin and metalloproteinase domain-containing protein ADAM10 leads to increased fibroblast activation and subsequently increased skin and lung fibrosis." (PMID 31333644, 2019). "Interestingly, ADAM10-mediated proteolytic shedding of ephrin-B2 promoted fibroblast recruitment and activation as well as lung fibrosis." (PMID 35280996, 2022). "In addition, pharmacological inhibition of ADAM10 by GI254023X prevented bleomycin-induced lung fibrosis in mice." (PMID 35280996, 2022). "A study found that ADAM10 is a major sheddase of ephrin-B2, and targeting ADAM10 with its inhibitor GI254023X could attenuate bleomycin-induced lung fibrosis in mice." (PMID 38071234, 2023).
multiple myeloma (6 papers, 2013 to 2025). "The authors found that ADAM10 upregulation on multiple myeloma cells was dependent on drug-induced production of reactive oxygen species." (PMID 32269567, 2020). "In a model of multiple myeloma, ADAM10 was prevailing with respect to ADAM17 in the MIC-mediated protease cleavage." (PMID 32269567, 2020). "Of interest, doxorubicin and melphalan increased both ADAM10 expression and activity on multiple myeloma cells and concomitant release of soluble MICA/B." (PMID 32269567, 2020). "In addition, an important role of ADAM10 in the regulation of MICA and MICB shedding in response to the treatment with genotoxic agents was demonstrated in multiple myeloma cell lines and in primary malignant plasma cells derived from patients." (PMID 32269567, 2020).
Obesity (6 papers, 2017 to 2026). Accumulation of substantial excess body fat. "In line with this hypothesis, genes PTK2B, KANSL1 and ADAM10 have been previously associated with obesity and BMI, while ABCA7 and ADAM10 have been associated with blood pressure." (PMID 34992629, 2021). "Targeting this pathway by limiting TREM2 shedding through ADAM10/17 inhibition may represent a promising therapeutic approach for mitigating adipose tissue inflammation and systemic metabolic dysfunction associated with obesity." (PMID 41509917, 2026). "Our findings extend these observations to adipose tissue, demonstrating that ADAM10/17-driven TREM2 cleavage similarly disrupts macrophage function in the context of obesity." (PMID 41509917, 2026). "While no data on ADAM10 expression or activity in obesity are available, plasma MMP-9 levels and its expression in fat tissue of obese subjects are increased." (PMID 28409494, 2017).
psoriasis (6 papers, 2019 to 2024). An autoimmune condition characterized by red, well-delineated plaques with silvery scales that are usually on the extensor surfaces and scalp. "Acitretin, a psoriasis medication, is another extensively studied repurposed drug for AD capable of inducing ADAM10 activity in vivo and clinically." (PMID 37266401, 2023). "Acitretin is a second generation retinoid, is in clinical use to treat the skin disease psoriasis, and activates ADAM10 expression in vitro and in mice." (PMID 30833305, 2019). "Acitretin, which is used in psoriasis as mentioned, acts due to the upregulation of metalloproteinase ADAM10, which can activate α-secretase and shift amyloid metabolism away from amyloidogenic fragments formed by cleavage of the amyloid peptide from amyloid precursor protein." (PMID 36226313, 2022). "Considering the recent emergence of several biologics for treatment refractory psoriasis, these ADAM10 inducers may provide a valuable and cost-effective first line treatment option for psoriasis." (PMID 32265938, 2020). "The second generation retinoid acitretin, which is in clinical use to treat psoriasis, mildly increases ADAM10 levels in vitro by 1.3‐fold and sAPPα levels in human CSF by 25% and, thus, was expected to also increase CSF levels of the cleaved ectodomain of other ADAM10 substrates in the brain." (PMID 30833305, 2019).
Senile plaques (6 papers, 2019 to 2021). Senile plaques are extracellular deposits of amyloid in the gray matter of the brain. "Overexpression of ADAM10 decreases the formation of senile plaques but increases the secretion of sAPPα in an animal model of AD, while overexpression of the ADAM10 inactive mutant form increases the formation of senile plaques." (PMID 32028607, 2020). "In this manner, ADAM10 may actually be protective in AD and prevent the formation of senile plaques." (PMID 33929683, 2021). "In addition to D-Pen chelating metals in senile plaques to reduce the accumulation of Aβ, our in vitro and in vivo results revealed that ADAM10 significantly increased the level of APPα expression in the brain and extracellular space." (PMID 33935689, 2021). "However, the α-secretase A Disintegrin And Metalloprotease 10 (ADAM10) is involved in a secondary and understudied pathway of APP processing that releases the soluble portion (sAβPPα) and prevents the formation of senile plaques." (PMID 33929683, 2021).
diabetic nephropathy (5 papers, 2017 to 2023). "Moreover, the ADAM10-mediated shedding of CX3CL1 has been linked to diabetic nephropathy, where increased levels of soluble CX3CL1 contribute to kidney injury and fibrosis." (PMID 37762417, 2023). "In diabetic nephropathy (DN), the expression of ADAMs is upregulated, while in our previous study, we demonstrated a reduced protein expression of ADAM10 in human cultured podocytes and glomeruli." (PMID 37513824, 2023). "Similarly, regulation of CXCL16 and ADAM10 expression is considered to be an early response in diabetic nephropathy development." (PMID 35335970, 2022). "GLEPP1, ADAM10, and NFκB may be considered additional candidate molecules indicative of early diabetic nephropathy." (PMID 28484521, 2017).
epilepsy (5 papers, 2017 to 2019). A brain disorder characterized by episodes of abnormally increased neuronal discharge resulting in transient episodes of sensory or motor neurological dysfunction, or psychic dysfunction. "In light of the effects of these substrates, the potential pathogenic mechanisms of ADAM10 in epilepsy are grouped into amyloidogenic processes in the ageing stage and cortical dysplasia in the developmental stage." (PMID 31087543, 2019). "Intriguingly, transgenic models have demonstrated ADAM10 to be associated with epilepsy." (PMID 31087543, 2019). "Beyond its role as a pathological hallmark of epilepsy, we hypothesized that neuroinflammation could affect the process of Adam10-regulated epileptogenesis." (PMID 30075790, 2018). "Additionally, Adam10 expression has been found to be altered in the dentate gyrus of kainic acid-induced epileptic rats, indicating an association of Adam10 with epilepsy." (PMID 30075790, 2018). "Moreover, a dominant negative variant of ADAM10 seemed protective against this form of experimental epilepsy as shown e.g., by decreased neuronal damage score." (PMID 28367112, 2017). "However, it is undetermined whether these variations affect ADAM10 translation or confer genetic susceptibility to ADAM10‐related diseases, especially epilepsy." (PMID 31087543, 2019). "miRNA/ADAM10 pathways have been primarily defined in tumours and AD but are undetermined in epilepsy." (PMID 31087543, 2019). "We subsequently review the potential pathogenic and regulatory mechanisms of ADAM10 and then discuss the stage‐dependent significance of ADAM10 in epilepsy." (PMID 31087543, 2019). "An increasing body of evidence indicates that ADAM10 is involved in various neurological disorders including epilepsy." (PMID 31114485, 2019). "Adam10 has been suggested to be involved in the neuroinflammation process under the conditions of epilepsy." (PMID 30075790, 2018). "Recent studies shed light on the link between Adam10 and another neurological disease, such as epilepsy." (PMID 30075790, 2018). "Our findings provide new insights into the Adam10 regulation of development of epilepsy via the neuroinflammation pathway and identify a potential therapeutic target for epilepsy." (PMID 30075790, 2018). "The role of ADAM10 in epilepsy is complex, however, since conditional ADAM10 knock-out mice also showed seizures." (PMID 28367112, 2017). "Recently, it has been reported that ADAM10 functions as a regulator of neuronal network activity and may play a crucial role in the pathological process of epilepsy." (PMID 31114485, 2019). "The regulation of the miR-23a-ADAM10 pathway in the epileptic brain may offer a novel approach for the treatment of epilepsy." (PMID 31114485, 2019). "Thus, the role of miRNAs in ADAM10 regulation should be explored in the context of epilepsy pathology." (PMID 31087543, 2019). "Our results suggest that modulation of miR-23a-ADAM10 pathway could play a pivotal role in the development of epilepsy." (PMID 31114485, 2019). "Therefore, it is plausible that the Adam10 gene regulates the development of epilepsy via modulation of hippocampal neural circuit activities." (PMID 30075790, 2018). "Based on these facts, we speculate that Adam10 plays an important role in the development of epilepsy through regulation of neural activities in the hippocampus." (PMID 30075790, 2018). "Our results suggest that the modulation of hippocampal neuroinflammation via Adam10 could play a pivotal role in the development of epilepsy." (PMID 30075790, 2018). "Thus, the miR-23a-ADAM10 pathway in the epileptic brain may provide a novel target for the treatment of epilepsy." (PMID 31114485, 2019). "Hence, ADAM10 most likely functions as a stage‐dependent modulator in the pathology of epilepsy." (PMID 31087543, 2019). "Therefore, ADAM10 is reviewed here as a stage‐dependent modulator in the pathogenesis of epilepsy." (PMID 31087543, 2019).
epilepsy (continued). "A growing body of evidence suggests that ADAM10 may also play an important role in epilepsy." (PMID 31114485, 2019). "Hence, targeting the integral modulation of Aβ and the AICD could be a strategy for treating epilepsy, and the upstream molecule ADAM10 could be a promising candidate for modulating amyloidogenic processes." (PMID 31087543, 2019). "In addition to regulatory region polymorphisms, exon mutations are also important; however, missense mutations of ADAM10 in epilepsy patients have not been reported in whole‐exome sequencing clinical studies." (PMID 31087543, 2019). "Thus, different disease mechanisms could play a role and additional work is needed before the role of ADAM10 in epilepsy can be assessed." (PMID 28367112, 2017).
HIV-1 infection (5 papers, 2011 to 2024). The type species of lentivirus and the etiologic agent of acquired immunodeficiency syndrome (AIDS). "In comparison, individual ADAM10 and 17 inhibitor, GI254023X and TAPI-0, respectively, fail to significantly suppress the viral infections, suggesting the involvement of both ADAM10 and 17 in HIV-1 infections." (PMID 38572241, 2024). "Their inhibition of HIV-1 infections correlated with enzymatic suppression of both ADAM10 and 17 activities and expressions of these ADAMs were transiently induced during the viral infection." (PMID 38572241, 2024). "As GI254023X distinguished ADAM10 and 17 enzymatic activities, we investigated the effect of their specific inhibition to HIV-1 infection using either GI254023X or TAPI-0, a known ADAM17 inhibitor." (PMID 38572241, 2024). "Thus, HIV-1 infection induced transient expressions of ADAM10 and 17 in the infected cells." (PMID 38572241, 2024). "To investigate the contribution of individual ADAM to HIV-1 infection, we infected CD8-depleted PBMC with a replication competent R5 tropic HIV-1BAL in the presence of either ADAM10 or 17 specific or broad specificity inhibitors and analyzed the intracellular p24 levels on day 7 of post infections." (PMID 38572241, 2024). "Over-expression of ADAM10 E384A showed an increase in HIV-1 replication very similar to that seen with wt ADAM10 over-expression, suggesting that the metalloprotease domain is not the critical domain in ADAM10 supporting HIV-1 infection." (PMID 21569301, 2011). "Finally, the involvement of multiple ADAMs is consistent with our observation that single specificity ADAM inhibitors alone, such as potent ADAM17 inhibitor 14mb or ADAM10 inhibitor GI254023X, were less effective than broad specificity inhibitor BB-94 in suppressing HIV-1 infection." (PMID 38572241, 2024). "Both ADAM10 and 17 can cleave CD62L for shedding and both appeared to be involved in HIV-1 infection as the single specificity inhibitors generally failed to suppress the viral infection." (PMID 38572241, 2024).
leukemia (5 papers, 2020 to 2025). A malignant (clonal) hematologic disorder, involving hematopoietic stem cells and characterized by the presence of primitive or atypical myeloid or lymphoid cells in the bone marrow and the blood. "CD58 and ADAM10 have been implicated in leukemia progression and chemoresistance; however, their specific roles in acute lymphoblastic leukemia (ALL) and chronic lymphocytic leukemia (CLL), particularly under chemotherapeutic pressure, remain insufficiently characterized." (PMID 40746920, 2025). "Taken together, the results of -omics profiling and functional tests revealed that genetic ablation or pharmacological inhibition of ADAM10 impaired leukemia cell cycle progression and survival." (PMID 37422628, 2023). "Loss of ADAM10 reduced LSC frequencies in both PDX models, indicating that LSC depend on ADAM10 to induce leukemia." (PMID 37422628, 2023). "In the SEM leukemia cell line, 854 proteins were down- and 1120 proteins upregulated upon ADAM10 KO, showing an activation of processes such as apoptosis/cell death, cell cycle, metabolism and membrane/adhesion upon KO." (PMID 37422628, 2023). "Ultra-sensitive proteomics allowed addressing the minute population of in vivo dormant PDX leukemia stem cells, while in vivo CRISPR/Cas9 dropout screens revealed leukemia dependence on ADAM10." (PMID 37422628, 2023). "To gain insights into the downstream effects of ADAM10 in leukemia, we performed proteome and transcriptome profiling of AL cells with or without ADAM10 expression." (PMID 37422628, 2023). "Of note, in ALL-199 and ALL-265, the number of ADAM10 KO cells in the BM was already reduced in the early stage of leukemia and decreased further during steady-state leukemia, indicating that ADAM10 KO affected both, cell homing and proliferation." (PMID 37422628, 2023). "Because LSC represent the most important targets for anti-leukemia treatment due to their unique ability to induce disease relapse, we next determined the effect of ADAM10 KO on stem cells." (PMID 37422628, 2023). "Inhibiting ADAM10 affected the leukemia-niche interaction, eliminated leukemia stem cells and fostered the anti-leukemia effect of conventional chemotherapy." (PMID 37422628, 2023). "It will be attractive to use our advanced technologies to investigate additional therapeutic targets in leukemia and to further explore ADAM10 inhibitors as components of chemotherapy regimens for acute leukemias." (PMID 37422628, 2023). "In line with this, the release of soluble ectodomains due to heightened ADAM10 activity might themselves act as signaling molecules, potentially fostering survival and proliferation signals in leukemia cells." (PMID 40746920, 2025). "Indeed, preclinical evidence suggests that ADAM10 inhibition can augment the efficacy of conventional chemotherapy in leukemia models." (PMID 40746920, 2025). "Studies have identified ADAM10 as the primary sheddase of CD23, a molecule of relevance in CLL, and have implicated its role in Notch signaling, a pathway frequently dysregulated in various cancers, including leukemia." (PMID 40746920, 2025). "Consequently, ADAM10 inhibition disrupts leukemia cell homing, reduces stem cell frequency, and enhances chemosensitivity in preclinical models." (PMID 40746920, 2025). "- In vivo PDX CRISPR-Cas9 screens identify ADAM10 as essential for leukemia in mice." (PMID 37422628, 2023). "Given the important role of both the in vivo microenvironment and LSC in mediating drug responses, we asked whether targeting ADAM10 may sensitize leukemia cells toward routine chemotherapy used to treat ALL or AML patients." (PMID 37422628, 2023). "- ADAM10 knockout impairs the leukemia-niche interaction and stem cell numbers." (PMID 37422628, 2023). "- Therapeutic targeting of ADAM10 reduces PDX leukemia fitness and augments therapy." (PMID 37422628, 2023).